MYC (MYC proto-oncogene, bHLH transcription factor)
Diseases named in the same sentence as MYC in open-access papers (continued):
Sharing a sentence is not in itself a finding about the gene and the disease.
tumor (continued). "In Eμ-myc transgenic mice, MYC directly upregulates PRMT5 and tumor progression is delayed after heterozygous deletion of the PRMT5 gene." (PMID 33989303, 2021). "Downregulated FTO expression substantially increases the m6A modifications on MYC, resulting in the binding of YTHDF1 to promote MYC mRNA translation and tumor cell glycolysis and growth." (PMID 33966037, 2021). "The let-7 family of miRNAs are well described tumor suppressors and are known to target several oncogenes including RAS, MYC and HMGA2." (PMID 33531067, 2021). "We have recently demonstrated that heme binding to G4 mitigates the interaction between the c-MYC promoter and the G4-interacting proteins nucleolin, NM23-H2 and hnRNPK, resulting in increased c-MYC expression and facilitating tumor growth and metastasis." (PMID 34359970, 2021). "Inserts showing c-MYC+, c-JUN+, Δp63+ LSCC tumours in mice receiving vehicle but partial positive or negative LSCC lesions in mice receiving FT206." (PMID 34636321, 2021). "In summary, our data strongly suggest an important role of the oncogene c-MYC in murine livers for MAFLD initiation and subsequent tumor promotion." (PMID 35008356, 2021). "The MYC family member c-MYC and MYCN are the most frequently deregulated oncogenes in human cancer and promote tumor progression through multiple levels of mechanisms in particular reprogrammed metabolism." (PMID 34235156, 2021). "(D) Quantification of c-MYC+ (LADC n = 33, LSCC n = 34), c-JUN+ (LADC n = 33, LSCC n = 33), and Δp63+ cells (LADC n = 41, LSCC n = 41) in LADC and LSCC tumours." (PMID 34636321, 2021). "Taken together, this data strongly suggests that MGA mediates ncPRC1.6 binding to MYC and E2F targets in human LUAD tumor cells." (PMID 34236315, 2021). "The three pH-LAMP tests (hTERT mRNA, MYC mRNA and TERC DNA) each had poor sensitivity but excellent specificity for predicting the presence of residual tumor." (PMID 34790573, 2021). "siRNA-mediated USP28 but not USP25 depletion, and USP28 inhibitor treatment, considerably reduced protein levels of Δp63, c-JUN, and c-MYC and impaired growth in human LSCC tumour cells." (PMID 34636321, 2021). "MYC is an uncommon driver of DIPG, and of the DIPG models tested here, SU-DIPGVI has a single copy of MYCN and c-MYC, while HSJD-DIPG007 is c-MYC amplified with a single MYCN copy, suggesting other driving factors in this tumor." (PMID 33579942, 2021). "Our results showed that BO administration enhanced the phosphorylation level of ERK (Thr202/Tyr204) and decreased the expression of MYC in the CRC cells and tumor tissues." (PMID 34869511, 2021). "The tumor suppressor miR-203a is significantly decreased in the H1975GR cells and has previously been identified as a regulator of MYC transcription." (PMID 33946744, 2021). "MXD3 is a transcription factor belonging to the MYC/MAX/MXD transcriptional network, and its expression is increased in tumor tissues." (PMID 34671559, 2021). "The majority of tumor cells from six of the patients analyzed were assigned to the group with abnormal activation of WNT/β-catenin and MYC signaling pathways, frequent somatic copy number alterations (SCNAs), and no hypermutation." (PMID 34833475, 2021). "(E) Immunoblot analysis of LADC tumours probed for USP28, c-MYC, c-JUN, SFTPC, cleaved caspase-3 (CC3)." (PMID 34636321, 2021). "In our previous studies, we explored the ability of a potent BRD4 inhibitor NHWD-870 shows great tumor suppressive potential in multiple solid tumors by depleting phosphorylated BRD4 and c-MYC." (PMID 34168981, 2021).
tumor (continued). "Interestingly, we observed an enrichment of E2F and MYC targets in poorly differentiated tumor foci compared to adenocarcinoma, suggesting that E2F and N-Myc may have altered or enhanced activity in the transition from adenocarcinoma to a poorly differentiated state." (PMID 34099734, 2021). "Positivity for c-MYC was defined as cases where ≥40% tumors cells reacted with any intensity; positivity for TTF-1 expression was defined cases where >10% of the tumor cells reacted with any intensity." (PMID 34513663, 2021). "There are multiple transcriptional factors, such as MYC, EZH2, TRIM24, KLF4, and BRD4, that can regulate AR transcription by binding to its promoter in tumor cells." (PMID 34323404, 2021). "ACTL6A overexpression promoted, while silencing ACTL6A suppressed cell proliferation and tumor growth in TNBC cells in vitro and in vivo, which was dependent on MYC signaling." (PMID 33541412, 2021). "As to how HAT1 regulates AR expression, there are multiple transcriptional factors, such as MYC, EZH2, TRIM24, KLF4, and BRD4, regulate AR transcription by binding to its promoter in tumor cells." (PMID 34323404, 2021). "The combination resulted in marked tumour suppression in vivo, supporting dual proteasome/HDAC inhibition as a potential therapeutic approach for MYC-driven cancers." (PMID 34884690, 2021). "In the present study, the MSI frequency of tumor-related genes, except BBC3 and MYC, was higher in B5-MSI tumors than in B5-MSS tumors, suggesting that the B5 panel is a powerful tool for defining the MSI status of CRC." (PMID 34563193, 2021). "It has also been shown that MiR-140-3p (a tumour-suppressive miRNA) targets BRD9 mRNA, downregulating MYC and reducing proliferation." (PMID 34944438, 2021). "Thresholds for tumor marker detection for Group1 were set from Group2 analysis (any hTERT, TERC/GAPDH 3.12, MYC/GAPDH 0.155)." (PMID 34790573, 2021). "Myeloid-derived suppressor cells (MDSCs) were one kind of immune cells leading to tumor immune escape, which was verified with cell colony formation, tumor sphere formation, and CSC biomarkers (NANOG and c-MYC)." (PMID 34745015, 2021). "MB0 is involved in the interaction with transcription elongation factors and in tumor growth acceleration, while MBI seems to have a role in ubiquitin/proteasome-dependent MYC degradation." (PMID 33801599, 2021). "Let-7 employs its antiproliferative activities and its tumor-suppressor role by controlling key checkpoints of several mitogenic pathways and by suppressing different oncogenes, including HMGA2, RAS, and MYC." (PMID 34442460, 2021). "c-MYC (green) was also co-expressed with NANOG (red), SOX2 (red) and KLF4 (red) by cells within the tumor glands (arrowheads)." (PMID 34685477, 2021). "In the next step, expression level of stemness relatedgenes (OCT4, SOX2, KLF4, c-MYC and NANOG) and EMTtranscription factors (CDH1, CDH2, SNAIL1, TWIST1,TWIST2 and ZEB1) were evaluated in all tumor samples andmammospheres." (PMID 31376329, 2020). "AR can modulate the expression of TFs, biomarkers and vital tumour promoters in PrCa development, such as KLK2, KLK3, MYC, MSMB and TMPRSS2." (PMID 32397189, 2020). "This is supported by observations in TRAMP-C1 allografts versus MyC-CaP; a greater CD45+ cell infiltrate at baseline and following RT; RT-induced altered expression of immune-related genes on NanoString; and reduced tumour growth rate." (PMID 32641865, 2020). "Several studies have modulated MYC paralog signaling through inhibition of BET, which resulted in promising anti-tumor effects against multiple cancer types, including SCLC." (PMID 33134168, 2020).
tumor (continued). "FOXM1 controls the expression of genes such as MYC, CCNB1, AURKB, and SKP2, which are essential for cell cycle progression at DNA replication and mitosis, and therefore important for tumor initiation and progression." (PMID 32083000, 2020). "In the total number of tumour samples from groups A, B, and C, PKM2 mRNA expression was significantly correlated with MYC mRNA expression (ρ2 = 0.153, p = 0.004)." (PMID 32722474, 2020). "Both c-MYC and β-catenin/TCF-Lef regulate the expression of several proteins that are important in tumour development, including survivin and VEGF." (PMID 33081077, 2020). "The knockdown of TRIB3 in EC cells causes a reduction in cell proliferation, migration, invasion, CSC activity, and in vivo tumor formation through the inhibition of cancer stemness genes, such as BMI1, OCT4, Nanog, β-catenin, and c-MYC." (PMID 33334065, 2020). "Knockdown of BAP18 decreased MYC, CCND1, KCNK5, and FOXC1 mRNA expression in xenograft tumor tissue." (PMID 32986841, 2020). "Here, we demonstrate the presence of an OCT4+/SOX2+/KLF4+/c-MYC+ CSC subpopulation within the tumor nests (TNs) and another within the peritumoral stroma (PTS), in this tumor." (PMID 32019273, 2020). "One patient (St23784/17) had amplifications in the 3q, 6q, 8q, 9q, and 10q22.1 regions of stemness gene localization in her tumor (the following genes were amplified: SOX2, MYC, KLF4, NOTCH1, NODAL)." (PMID 32523653, 2020). "Other compounds that target the DNA binding domain of the MYC–MAX complex such as KSI-3716, MYCi975, sAJM589, and 10074-G5 were found to have anti-tumor effects in multiple tumor cell types." (PMID 32748879, 2020). "The let-7 family is considered a tumor suppressor because it inhibits the expression of multiple oncogenes, including RAS, MYC, and HMGA2." (PMID 32089682, 2020). "For instance, the tumor suppressors PTEN and RB1 were frequently lost, while the oncogene MYC was inside a frequently amplified region, confirming the validity of the SCNA analysis to pinpoint genes relevant to tumor progression." (PMID 32858747, 2020). "The drug combination enhanced the overall survival rate of tumor-bearing BALB-bclxl transgenic mice and lowered MYC protein levels in tumors of these immunocompetent mice." (PMID 32923678, 2020). "Overall, the immunomodulatory effects of MYC oncogene in PDAC mainly happen via increased expression of PD-L1 and CD47 to evade both innate and adaptive immune responses, thus favoring tumor growth." (PMID 32664564, 2020). "The recently discovered MYC inhibitor 361 (MYCi361) binds to the HLH region of the MYC protein (AA366-378), disrupts MYC/MAX heterodimerization, enhances degradation of both MYC and MYCN, and suppresses MYC-dependent tumor cell growth in vitro and in vivo." (PMID 33628735, 2020). "PP2A is generally considered as a tumor suppressor that dephosphorylates multiple critical oncogenic proteins, such as Akt, extracellular signal-regulated kinase (ERK), and MYC." (PMID 33275593, 2020). "MYC paralogs, including c-MYC, MYCL, and MYCN, play a pivotal role in tumorigenesis and tumor maintenance through regulation of a variety of cellular processes." (PMID 33134168, 2020). "The concordance between the FISH results of HER2 and c-MYC in CTC and archival tumor tissue showed the potential of using CTC FISH assays for determining the gene status of HER2 and c-MYC in GC patients." (PMID 31454863, 2020).
tumor (continued). "MYC acts as a transcriptional factor that regulates the transcription of over 15% of human genes, such as CCND, CDK4 and E2F1, which are involved in tumour progression." (PMID 31907353, 2020). "Metformin blocks the tumour-promoting effects of NGF in EOC cells modulating several oncoproteins such as VEGF, c-MYC and survivin, as well as c-MYC and β-catenin/TCF-Lef transcriptional activity." (PMID 33081077, 2020). "Several small-molecule inhibitors of the MYC-MAX interaction have been reported 24, 33-36 but all were challenged by rapid metabolism and poor bioavailability, leading to poor anti-tumor responses." (PMID 32685002, 2020). "The results show that the phosphorylation of p-MEK and the expression of MYC, JUN and PDCD6 were higher in tumor tissues than in adjacent normal tissues." (PMID 32746883, 2020). "miR-487b and miR-203 have been noted to work as tumor suppressive miRNAs in lung cancer by targeting KRAS, WNT5A, SUZ12, MYC, and BMI1 (miR-487b) and FZD2 (miR-203)." (PMID 32316322, 2020). "Previously, KJ-Pyr-9 as inhibitor of both MYC and NMYC showed proliferation inhibiting effects on various tumor cell lines." (PMID 32927768, 2020). "The MYC v1 and v2 scores, specifically in ER-positive/HER2-negative tumors, were found to correlate to tumor aggressiveness." (PMID 33143224, 2020). "One population within the tumor niche had the markers SOX2+/NANOG+/KLF4+/c-MYC+/OCT4−, and two populations in the peritumoral stroma had the markers SOX2+/NANOG+/KLF4+/c-MYC+/OCT4− and SOX2+/NANOG+/KLF4+/c-MYC+/OCT4+." (PMID 32974184, 2020). "We used MYC, CCNA1, and BIRC7 in combination as a D-marker panel for identifying depressed neoplasms, and tested the panel in the discovery set." (PMID 32532105, 2020). "Targeting of the MYC paralog-PARP1-DDR signaling pathway using the combination of BETi JQ1 and PARPi BMN673 demonstrated excellent anti-tumor efficacy in MYC paralog-dependent SCLC cells." (PMID 33134168, 2020). "Inhibiting MYC on NSCLC in mice, lead to rapid regression of tumours with mild reversible side effects." (PMID 33255394, 2020). "Overexpression of miR-145 in ovarian cells was used to evaluate cell proliferation, migration, invasion, c-MYC and VEGF protein levels, as well as tumor formation and metastasis in vivo." (PMID 33081171, 2020). "F. nucleatum infection enhanced the tumor growth of CRC in a TLR4-dependent manner, and the effect involved activation of the IL-6/p-STAT3/c-MYC signaling pathway." (PMID 33488528, 2020). "Immunohistochemical analysis of the tumor tissues revealed a statistically significant (P-value < 0.05) reduction in staining for HSP70, MYC, BRD4, and αSMA in Minnelide-treated mice." (PMID 33168807, 2020). "In NSCLC tumor tissues and A459 cell line, HOTAIR would also upregulate CSC-related biomarkers such as NANOG, POU5F1, SOX2, MYC, CTNNB1, and KLF4." (PMID 32438606, 2020). "However, there are already reported studies successful inhibiting MYC in tumor-associated macrophages, demonstrating that a better understanding of the role of MYC in the tumor microenvironment and metastasis could represent an effective way to successfully target MYC in cancer." (PMID 33081056, 2020).
tumor (continued). "Our results show that metformin, strongly decreases c-MYC, β-catenin and VEGF expression in EOC cells with little effect on non-tumour ovarian cells." (PMID 33081077, 2020). "Possibly, MYC increases the levels of PTPRA, activating the function of this gene as a tumor suppressor, enabling cell signaling events, coordinating the control of proliferation, apoptosis, survival, migration and invasion." (PMID 33351778, 2020). "Our results identify strong contributions of epithelial-to-mesenchymal transition (EMT), classical tumor-promoting (such as E2F, KRAS, MYC, mTORC1, and TGFB1 signaling) and immune-related pathways in the tumor epithelium of COSCC." (PMID 33142242, 2020). "After MYC activation, there is a dramatic influx of CD206+ (also known as mannose receptor) TAMs in the tumor site." (PMID 33081056, 2020). "First, although Eμmyc/EμBCL‐2 murine tumors and EBV‐positive BL cells both overexpress MYC and BCL‐2 proteins, they have very different phenotypes: Eμmyc/EμBCL‐2 tumor cells have a lymphomyeloid progenitor phenotype, whereas BL cells have a GC phenotype." (PMID 32623836, 2020). "Additionally, MYC proteins also affect the tumor microenvironment; MYC protein was shown to regulate the interaction between tumor cells and the host immune cells by controlling the synthesis of cytokines mediating communication between tumor cells and myeloid cells." (PMID 33585251, 2020). "As such, the PIDDosome should exert tumor‐suppressive functions that may explain observations of increased rates of tumor formation in mice lacking caspase‐2, challenged by oncogenic drivers such as MYC or ERBB2, or concomitant ATM loss." (PMID 33225610, 2020). "Estrogen-induced genes, such as MYC, MTA3, CARM1 and so on, play vital roles in cell-cycle regulatory, tumor metastasis and endocrine treatment resistance." (PMID 32986841, 2020). "Of note, it was reported that mir-19 targeting decreased the expression of MYC and delayed GBM tumor growth." (PMID 32927769, 2020). "c-MYC interacts with histone methyltransferase EHMT2 to repress gene transcription, and knockdown of EHMT2 results in decreased tumor volume." (PMID 33628735, 2020). "CRIS-C encompasses CIN tumours with wildtype KRAS status, MYC amplification and increased EGFR pathway activity." (PMID 32647253, 2020). "Our results show that miR-145 levels decrease during EOC progression and that miR-145 upregulation decreases cell proliferation and c-MYC and VEGF levels in ovarian cells, as well as tumor size and the malignant presence of ascites in a mouse model." (PMID 33081171, 2020). "We propose as a possible general explanation for our findings that overexpression of MYC and TWIST1 in a tumor is activating an embryonic program of innate immune cell activation and cellular invasion." (PMID 31933479, 2020). "TCGA dataset mining was performed using UALCAN to shown that abnormal expression of the hub genes, including CDK1, VEGFA, PRDM10, RUNX1, CDK6, HSP90AA1, and MYC, were significantly up-regulated between ESCA primary tumor and normal tissues." (PMID 32662828, 2020). "The present study demonstrates that MYC, CCNA1, and BIRC7 alterations are significantly enriched in depressed neoplasms." (PMID 32532105, 2020). "By controlling MYC stability, CMA potentially exerts a key role in the regulation of the cell cycle and cell proliferation, and consequently, in tumor development." (PMID 32971884, 2020). "Further analysis showed that most CNAs, including amplification in AR and deletion in PTEN in P8, amplifications in ELF2 and MYC in P9, and amplifications in MYC and CCND1 in P11, were concordant in the plasma and tumor tissues." (PMID 32631448, 2020).